PDCD4 (programmed cell death 4)
Diseases named in the same sentence as PDCD4 in open-access papers (continued):
Sharing a sentence is not in itself a finding about the gene and the disease.
colorectal cancer (74 papers, 2008 to 2025). A primary or metastatic malignant neoplasm that affects the colon or rectum. "The expression of CAII has been found to correlate with biological aggressiveness in colorectal cancer, although this has yet to be associated with PDCD4 suppression." (PMID 35847932, 2022). "Decreased invasion after an increase in PDCD4 expression has been observed in colorectal cancer, which was associated with diminished Urokinase-type plasminogen activator receptor (uPAR) expression." (PMID 35847932, 2022). "miR-21 has also been shown to down-regulate the Programmed cell death protein 4 (PDCD4) tumor suppressor and its overexpression can cause stimulation of invasion and metastasis in colorectal cancer." (PMID 24690114, 2014). "Loss of Pdcd4 expression had been demonstrated to correlate with tumour grade, disease stage, recurrence and patient survival in lung and colorectal cancers." (PMID 19728867, 2009). "The invasive capability of Pdcd4 knockdown cells transfected with SLUG siRNA was reduced to approximately 45% compared to Pdcd4 knockdown cells transfected with scrambled siRNA, indicating that Slug up‐regulation caused by Pdcd4 knockdown contributes to invasion promotion in colorectal cancer cells." (PMID 40785580, 2025). "Besides, PDCD4 knockout also promoted AOM plus DSS-induced colorectal cancer by the mechanism that PDCD4 deficiency increased the macrophage-secreted IL-6 induced by DSS and elevated the epithelial cell susceptibility to IL-6/STAT3 pathway-mediated cell proliferation during malignant transformation." (PMID 33099584, 2020). "In agreement with these in vitro studies, Pdcd4 knockdown promotes metastasis in colorectal cancer HT29 and GEO cells when these cells were injected into the cecal wall of nude mice." (PMID 40785580, 2025). "PDCD4 shRNA and SLUG siRNA were used to knock down Pdcd4 and Slug in colorectal cancer cells, respectively." (PMID 40785580, 2025). "Specifically, the microRNA miR-21 has been demonstrated to enhance tumor invasion and metastasis, and its expression has been correlated with unfavorable prognoses by repressing programmed cell death-4 (PDCD4) in colorectal cancer patients." (PMID 40572694, 2025). "Snail and Slug are two important transcription factors to regulate EMT and Pdcd4 is a critical inhibitor for EMT in colorectal cancer." (PMID 40785580, 2025). "Programmed cell death 4 (Pdcd4), a tumor suppressor, is ubiquitously expressed in all of the tissues and is frequently down‐regulated in various types of cancers including colorectal cancer." (PMID 40785580, 2025). "In this study, we aimed to understand the impact of Slug on Pdcd4 knockdown‐induced colorectal cancer cell invasion and elucidate the mechanism by which Pdcd4 regulates Slug expression." (PMID 40785580, 2025). "This study demonstrated that the Pdcd4 regulates Slug protein translation to control E‐cadherin expression and invasion in colorectal cancer cells." (PMID 40785580, 2025). "The expression of miR-21 is frequently upregulated in colorectal cancer, and the target genes regulated by miR-21 include PDCD4, RhoB, and TGFβR2." (PMID 40693022, 2025). "We also show that the up‐regulation of Slug by Pdcd4 knockdown is functionally significant in terms of down‐regulating E‐cadherin expression and promoting cell invasion in colorectal cancer cells." (PMID 40785580, 2025). "In colorectal cancer, it inhibits proliferation and induces apoptosis by releasing PDCD4 through miR-196a decoying." (PMID 37958599, 2023). "Programmed cell death 4 (PDCD4), is a tumour invasion suppressor frequently downregulated in colorectal cancer." (PMID 37877351, 2023). "The loss of PDCD4 increases the translation of SIN1 thereby upregulating SNAIL expression and invasion of colorectal cancer cells." (PMID 37877351, 2023). "This is in direct contrast to evidence of PDCD4 translocation to the cytoplasm after PKB phosphorylation in resected colorectal cancer." (PMID 35847932, 2022).
colorectal cancer (continued). "PDCD4 is also targeted by miR-21, which stimulates the invasion and metastasis of colorectal cancer cells." (PMID 36685574, 2022). "Linc00472 suppresses tumor growth through sponging miR-196a to elevate PDCD4 expression in colorectal cancer." (PMID 32982585, 2020). "Another study found that curcumin downregulated miR-21 in colorectal cancer cells, which in turn upregulated the tumor suppressor gene programmed cell death 4 (PDCD4)." (PMID 30959836, 2019). "The tumor suppressor gene PDCD4 has been validated as a miR-21 target in prostate cancer, glioblastoma, retinoblastoma, lung cancer, thyroid carcinoma, colorectal cancer, and renal cell carcinoma." (PMID 28881718, 2017). "PDCD4 expression in poorly-differentiated colorectal cancer, gastric cancer, and pancreatic cancer was lower than in highly-differentiated cancers, and deletions in or decreased expression of PDCD4 correlated with poor prognosis." (PMID 28423589, 2017). "In contrast, in colorectal cancer cells overexpressing PDCD4, E-cadherin protein level was increased accordingly." (PMID 27852288, 2016). "Pdcd4 suppression by miR-21 induced invasion, intravasation, and metastasis of colorectal cancer cell lines in chicken-embryo-metastasis assay." (PMID 27027350, 2016). "Programmed cell death 4 (PDCD4) is a RNA-binding protein that acts as a tumor suppressor in many cancer types, including colorectal cancer (CRC)." (PMID 27647131, 2016). "miR-21 was found to be highly expressed in colorectal cancers, and induced metastasis and invasion by inhibiting the tumor suppressing gene PDCD4 in colorectal cancer cells." (PMID 26134825, 2015). "For example, miR-21 was found to be highly expressed in colorectal cancers, and induced metastasis and invasion by inhibiting the tumor suppressing gene PDCD4 in colorectal cancer cells." (PMID 25560389, 2015). "miR-21 is a potent stimulator of tissue and vascular invasion in colorectal cancer and these effects appear in part mediated by its ability to prevent translation of one of the miR-21 target genes, Programmed Cell Death 4 (PDCD4)." (PMID 25310697, 2014). "The inflammation induced cyclooxygenase 2 (COX-2) enzyme required for the production of Prostaglandin E2 (PGE2), can promote colorectal cancer by decreasing expression of the tumour suppressor gene Programmed Cell Death 4 (PDCD4)." (PMID 25310697, 2014). "Our study provides mechanistic insights into the link between inflammation, miR-21 and PDCD4 expression and colorectal cancer progression." (PMID 25310697, 2014). "In a study of colorectal cancer, PDCD4 mRNA levels were negatively regulated by miR-21 at each stage of cancer." (PMID 24959246, 2014). "Asangani and colleagues originally reported that miR-21 posttranscriptionally downregulates PDCD4, as measured in as many as ten different colorectal cancer cell lines." (PMID 25400316, 2014). "MiR-21 has been shown to target the expression of phosphatase and tensin homologue (PTEN) in hepatocellular cancer, programmed cell death 4 (PDCD4) in colorectal cancer and Sprouty2 (SPRY2) in cardiocytes." (PMID 24497923, 2014). "miR-21 mediates anti-apoptotic and metastatic effects by regulating programmed cell death 4 (PDCD4) in colorectal cancer, and miR-21 is a downstream effector of AKT that exerts its anti-apoptotic effects via the suppression of Fas ligand in hypoxic conditions." (PMID 24194922, 2013). "The microRNA has been shown to downregulate expression of tumor suppressor gene Pdcd4 in colorectal cancer cells, thereby stimulating tumor invasion, intravasation and metastasis." (PMID 22363450, 2012). "An inverse correlation of PDCD4 and p-Akt expression has been reported in colorectal cancer tissue samples." (PMID 22272332, 2012).
colorectal cancer (continued). "For example, miR-21 decreases tumor suppressor Pdcd4 expression and promotes invasion, intravasation and metastasis in colorectal cancer." (PMID 22363450, 2012). "It was also found that Pdcd4 is inversely correlated with miR-21 levels in colorectal cancer cell lines as well as the resected tumor tissues of 22 colorectal cancer patients." (PMID 19440450, 2008). "Additionally, miR-21 facilitates colorectal cancer progression by targeting tumor suppressor messenger RNAs, including tropomyosin 1, programmed cell death 4 (PDCD4), and phosphatase and tensin homolog (PTEN)." (PMID 41398969, 2025). "Next, we transfected the Pdcd4 expressing plasmid along with SLUG‐5′UTR‐Luc into colorectal cancer RKO cells to test whether Pdcd4 inhibits the translation of SLUG‐5′UTR‐Luc." (PMID 40785580, 2025). "Pdcd4 suppresses colorectal cancer invasion by translationally downregulating Slug expression." (PMID 40785580, 2025). "Therefore, inhibition of Slug translation by Pdcd4 results in suppression of colorectal cancer cell proliferation and invasion." (PMID 40785580, 2025). "Thus, our results indicate that translational up‐regulation of Slug expression by Pdcd4 knockdown contributes to invasion promotion in colorectal cancer cells." (PMID 40785580, 2025). "In colorectal cancer, PDCD4 inhibits SIN1 (MAPKAP1) translation, to reduce cell invasion." (PMID 39890941, 2025). "Since Pdcd4 knockdown up‐regulates Snail expression, it is interesting to examine whether Pdcd4 also regulates Slug expression in colorectal cancer cells." (PMID 40785580, 2025). "In colorectal cancer, miR-21 can down-regulate transforming growth factor β receptor 2, inducing stemness, stimulating invasion, and stimulating metastasis by suppressing PDCD4." (PMID 36140324, 2022). "Similarly, LINC00472 was found to promote cell apoptosis and suppresses cell proliferation through elevating PDCD4 expression by sponging miR-196a in colorectal cancer." (PMID 36371410, 2022). "Therefore, except for indicating cancer progression by integrin β4, the combination of high miR-21 and low ITGβ4 and PDCD4 expression can predict the presence of metastasis and can be used as a predictive tool for colorectal cancer metastasis." (PMID 34439865, 2021). "In colorectal cancer cell lines, miR-21 is negatively correlated with the protein Pdcd4." (PMID 34439865, 2021). "Furthermore, miR-196a overexpression or PDCD4 knockdown reversed Linc00472-mediated proliferation inhibition and apoptosis induction in colorectal cancer cells." (PMID 29930217, 2018). "Our study demonstrated that Linc00472 suppressed proliferation and induced apoptosis through up-regulating PDCD4 by decoying miR-196a, which may be an effective therapeutic target for colorectal cancer." (PMID 29930217, 2018). "More recently, miR-499 was shown to also regulate PDCD4 in colorectal cancer." (PMID 26867589, 2016). "Further, in colorectal cancers, miR-21 inhibits apoptosis and invasion by regulating Pdcd4." (PMID 23469214, 2013). "Additionally, it has been verified that miR-21 overexpression can down-regulate the Pdcd4 tumor suppressor and stimulate invasion, intravasation and metastasis in colorectal cancer." (PMID 21176238, 2010). "Additionally, miR-21 decreased PDCD4 levels and increased invasion and metastasis in colorectal cancer." (PMID 20831814, 2010). "For instance, the lncRNA maternally expressed gene 3 (MEG3) (NCBI GeneID: 55384) is located at chromosome 14q32 and could enhance the sensitivity of colorectal cancer (CRC) cells to oxaliplatin via the upregulation of PDCD4 by sponging miR-141 and overcoming oxaliplatin resistance in CRC." (PMID 31620370, 2019). "In colorectal cancer (CRC) cells, activated IL-6/STAT3 signals increased the expression of miR-181, which leaded to downregulating the expression of PDCD4 and promoting cell proliferation and metastasis and inhibit the apoptosis of CRC cells." (PMID 31620370, 2019).
colorectal cancer (continued). "Strong to moderate positive correlation was observed between PDCD4 and DFFA in esophageal cancer tissues (r = 0.657, P = 0.039), and between PDCD4 and ANXA1 in gastric carcinoma (r = 0.683, P = 0.007) and colorectal cancer (r = 0.617, P = 0.001)." (PMID 29091952, 2017). "A well-known oncomir, miR-21, overexpressed in various cancers including colorectal cancer, modulates the expression of PTEN (phosphatase and tensin homolog) and PDCD4 (Programmed cell death-4) genes involved in cell proliferation and apoptosis." (PMID 27681738, 2016). "As PDCD4 is also a direct target of the oncogene microRNA-21 (miR-21) we investigated the relationship between the COX-2 and miR-21 pathways in colorectal cancer progression." (PMID 25310697, 2014). "We have demonstrated a functional link between COX-2, miR-21 and PDCD4, which provides further understanding into the beneficial effects of COX-2 inhibitors in colorectal cancer control." (PMID 25310697, 2014). "It promotes the migration and invasion of colorectal cancer cells via regulating the expression of forkhead box O4 (FOXO4) and programmed cell death 4 (PDCD4)." (PMID 24194751, 2013). "Knockdown of Pdcd4 in colorectal cancer cells increased Slug protein levels without altering SLUG mRNA abundance." (PMID 40785580, 2025). "We systematically analyzed the prognostic value of transcription levels of SFs in colorectal cancer (CRC) and found that RAB3A interacting protein (RAB3IP), programmed cell death 4 (PDCD4), golgin B1 (GOLGB1), and neuregulin 4 (NRG4) as the most predictive markers for the prognosis of CRC." (PMID 40657366, 2025). "Notably, hsa-miR-21-5p, which is upregulated in colorectal cancer, has been shown to target genes involved in apoptosis and inflammatory responses, such as TGFBI and PDCD4, both of which were also found to be downregulated in our study." (PMID 39336798, 2024). "Interestingly, the resistant cells exhibit relatively low levels of Pdcd4 protein, while sensitive cells show high Pdcd4 levels, suggesting a correlation between Pdcd4 expression and chemosensitivity to OSI-906 in colorectal cancer cells." (PMID 39459035, 2024). "Moreover, this study has contributed to an improved understanding of the role of miR-21, PDCD4 and COX-2 in colorectal cancer progression." (PMID 25310697, 2014). "In 2011, Liu and colleagues found that miRNA-499-5p could promote cellular invasion and tumor metastasis in colorectal cancer by targeting FOXO4 and PDCD4 and miRNA-499-3p (3746444 A>G) was found in an invasive breast cancer cell line." (PMID 23236400, 2012). "In addition, Pdcd4 protein level is also found to be downregulated in recurrent colorectal cancer patients compared to those with non-recurrent colorectal cancer." (PMID 39459035, 2024). "Moreover, in colorectal cancer tissues, the SIN1 protein but not mRNA was significantly upregulated, while PDCD4 protein was downregulated, confirming, in colorectal cancer patients, the connection between loss of PDCD4 and increased SIN1 protein level." (PMID 37877351, 2023). "Therefore, malignancy driver functions attributed in our work to p32 in colorectal cancer cells could be explained at least partly by its ability to significantly modify the transcription levels of HAS-2 and PDCD4 genes, and to its ability to activate the PI3K/Akt/mTOR signaling pathway." (PMID 34136383, 2021). "Programmed cell death 4 (PDCD4) was reported to downregulate p70S6K1 phosphorylation and translation, but not p70S6K2, leading to chemosensitivity of colorectal cancer (CRC) cells to the insulin-like growth factor 1 receptor (IGF1R) inhibitor linsitinib (OSI-906)." (PMID 35008473, 2021).
colon carcinoma (54 papers, 2006 to 2025). "PDCD4 was down-regulated or loss in many cancers and related to tumor progression and poor outcomes, such as colon cancer, ovarian cancer, glioblastoma and lung cancer." (PMID 31409387, 2019). "A recent study in PDCD4 knock-down colon cancer cell lines demonstrated that E-Cadherin loss is a key event for activating the β-catenin/Tcf-dependent transcription, leading to subsequent over-expression of the invasion-promoter genes u-PAR and c-MYC." (PMID 20831814, 2010). "Tnf-α not only promotes colon cancer cell migration and invasion but also represses Pdcd4, and Pdcd4 deficiency may aggravate inflammatory response." (PMID 34771727, 2021). "For example, in colon cancer, AA appears to regulate Pdcd4 through the PI3K/Akt/mTOR/p70S6K signaling pathways, which are well known to be the main pathways regulating proliferation, apoptosis, and migration of cancer cells." (PMID 38610995, 2024). "Colon cancer cells secrete miR-208b, which delivers to receptor T cells and promotes Treg proliferation by targeting programmed cell death 4 (PDCD4)." (PMID 39262952, 2024). "Berberine inhibited miR-21 expression and promoted integrin β4 (ITGβ4) and programmed cell death 4 (PDCD4) protein expression in colon cancer cell lines." (PMID 38004113, 2023). "For example, miR-21 promoted the invasion and metastasis of colon cancer tumor cells by down-regulating Pdcd4 in colon cancer." (PMID 34084160, 2021). "Berberine suppresses the viability of colon cancer cells and regulates the three-gene network microRNA (miR)-21-integrin β4 (ITGβ4)—programmed cell death 4 (PDCD4)." (PMID 34885950, 2021). "Studies showed that berberine induces the expression of integrin β4 and PDCD4 in colon cancer cell lines by inducing cell apoptosis and caspase-3 activity, and it inhibits the activity of miR-21 in colon cancer cells." (PMID 34439865, 2021). "In colon carcinoma cells, high levels of PDCD4 inhibited Akt signaling pathway, decreasing invasiveness." (PMID 32410997, 2020). "An example of such includes miR-21, which acts as an oncogene in colon cancer by inhibiting Pdcd4 and consequently increasing invasion and metastasis." (PMID 32338277, 2020). "We also report that several target genes of miR-21, such as, PDCD4, TPM1 and PTEN are down-regulated by exosomes from colon cancer cells, and, further, silencing of PDCD4 mimics the effects of miR-21 transfections." (PMID 32427870, 2020). "In this study, PDCD4–13086-ES is a diverse AS event, which means that the ES of PDCD4 plays roles as an oncoprotein in colon cancer." (PMID 32962686, 2020). "We first silenced PDCD4 in all of the three colon cancer cell lines, HT29, T84 and LS174 and observed the siRNA to be very effective in down-regulating PDCD4 levels (result not shown)." (PMID 32427870, 2020). "Conversely, PDCD4 knockdown stimulated cell proliferation by upregulating cyclin D1 expression in HT29 colon tumor cells." (PMID 31075975, 2019). "Among them, nucleotide anti-mir21 drugs inhibit colon cancer cell metastasis up-regulating PDCD4-protein levels in in vitro experiments." (PMID 31075975, 2019). "The regulation of Snail by PDCD4 was demonstrated through Akt, and the knockdown of Akt abolishes PDCD4 knockdown-induced Snail expression in colon cancer." (PMID 31620370, 2019). "In colon tumor cells, PDCD4 regulates the expression of the JNK upstream kinase MAP4K1 by c-Myc, resulting in the activation of JNK and c-Jun, to control the activation of AP-1." (PMID 31620370, 2019). "The anti-tumor activity of PDCD4 is well documented in invitro systems especially by using colon cancer cell lines and in Pdcd4 transgenic and knockdown mice." (PMID 31075975, 2019). "It has been reported that PDCD4 knockdown stimulates cell proliferation by up-regulating the cyclin D1 expression in HT29 colon carcinoma cells and keratinocytes." (PMID 30687637, 2018).